ESR1 (estrogen receptor 1)
Diseases named in the same sentence as ESR1 in open-access papers (continued):
Sharing a sentence is not in itself a finding about the gene and the disease.
invasive breast carcinoma (188 papers, 2005 to 2026). A carcinoma that infiltrates the breast parenchyma. "This mutant ER results from a frequent somatic mutation at nucleotide 908 of ESR1 (A908G) that is detected in premalignant breast lesions and invasive breast cancers." (PMID 38567308, 2024). "The results indicated that, in stages 3 and 4, the ESR1 gene expression levels were highly expressed in all invasive breast carcinoma patients; however, in subtypes such as Her2, Luminal A, and Luminal B, they were only expressed in stage 4." (PMID 39202273, 2024). "To conclude, the presented results showed that SFRP1 expression is positively correlated with ESR1 in non-tumoral breast tissue, while it is negatively correlated with ESR1 in invasive breast cancer." (PMID 37190179, 2023). "We found that the ESR1 mRNA was highly expressed in breast invasive carcinoma (BRCA) and OV samples compared with their matched normal samples." (PMID 34322374, 2021). "In this report, we evaluated risk factors for invasive breast cancer classified according to the presence or absence of the ESR1 A908G mutation in the CBCS, a population-based case-control study of breast cancer among younger and older white and African-American women in North Carolina." (PMID 17553133, 2007). "To further investigate molecular differences by race, we analyzed established IBC biomarkers by SRR, including gene expression of ESR1 (ER) and ERBB2 (HER2), as well as the intrinsic subtypes defined by PAM50 in invasive breast cancers." (PMID 39223670, 2024). "To define the co-expression relationship between SEMA3C and the estrogen receptor, we used mRNA expression data of SEMA3C and ESR1 from a TCGA study (Firehose Legacy-Breast Invasive Carcinoma) with 1100 samples." (PMID 37443749, 2023). "The correlation of ESR1 and AFF4 expression in the TCGA breast invasive carcinoma dataset with 971 completed tumors was calculated." (PMID 32265480, 2020). "Gene-level quantifications from RNA-Seq data of 1246 invasive breast cancer samples from The Cancer Genome Atlas were clustered based on their expression of HER2, ESR1, and PGR." (PMID 30279965, 2018). "To obtain molecular insights into these phenomena, we analyzed The Cancer Genome Atlas (TCGA) breast invasive carcinoma (BRCA) RNA-Seq datasets for the expression of ESR1 and its correlation to microRNAs (miRNAs) and long non-coding RNAs (lncRNAs), along with its methylation patterns." (PMID 40243758, 2025). "We have also shown for the first time that seven of the known invasive breast cancer predisposition loci not previously shown to be associated with DCIS have comparable ORs for IDC and DCIS: rs4973768 (SLC4A7), rs3821902 (ATXN7), rs10995190 (ZNF365), rs554219 (CCND1), rs3757318 and rs2046210 (ESR1)." (PMID 26884359, 2016). "However, in patients with Luminal A breast invasive carcinoma, there was a negative correlation found between ESR1 and CXCL3, CXCL5, and CXCL6 gene expression; and in Her-2 patients, the same relationship was seen between ESR1 and CXCL6." (PMID 39201290, 2024).
invasive ductal carcinoma (165 papers, 2005 to 2026). "In terms of histological subtype, the ESR1 hotspot mutations in invasive ductal carcinoma reflect visceral disease (44% are D538G)." (PMID 32374727, 2020). "This cell line is representative of estrogen receptor positive (ER+) invasive ductal breast carcinoma, which is known to be mainly driven by the combined activity of the TFs ESR1, GATA3, and FOXA1." (PMID 34174819, 2021). "RNA sequencing detected a novel in-frame fusion gene, ESR1-ARMT1, between ESR1, encoding estrogen receptor 1, and ARMT1, encoding acidic residue methyltransferase 1, in an ER+ luminal type invasive ductal carcinoma, case BR15-035T." (PMID 29464067, 2018). "ELF5 represses EMT by suppressing SNAI2 expression and down regulating ESR1, and down regulation of ELF5 is detected in all stages of cancer progression including atypical ductal hyperplasia, ductal carcinoma in situ and invasive ductal carcinoma." (PMID 29016359, 2017). "An incidental right invasive ductal carcinoma was additionally found on review of the pathologic specimen, which was 0.3 cm, grade 1 and strongly hormone receptor positive (estrogen receptor 100%, progesterone receptor 100%) and Her-2/neu negative (IHC score 1+)." (PMID 33507482, 2021). "In the T47D no-special type (invasive ductal carcinoma [IDC]-NST) cell line, overexpression of the most significant ESR1 fusion proteins revealed an estrogen response signature that was subsequently developed into a 24-gene signature as a biomarker for functional fusion activity." (PMID 39207954, 2024).
metastatic disease (143 papers, 2008 to 2026). "Most mutations of ESR1 gene appear in metastatic tumors treated by AIs, suggesting that mutations are related to the generation of cell metastasis phenotype." (PMID 41560039, 2026). "Our results are consistent with other reports that found these mutations to be frequent in metastatic tumors, as the ESR1 mutation is often an acquired mutation during or after the treatment with aromatase inhibitors, and associated with a worse prognosis." (PMID 40647516, 2025). "The high prevalence of ESR1 point mutations in ERα−positive metastatic tumors indicates that ER dependency persists throughout tumor progression, driving acquired resistance." (PMID 40641933, 2025). "The prevalence is increasing in later lines and longer metastatic disease due to ESR1 mutation acquisition." (PMID 40361341, 2025). "ESR1 mutations are likely drivers of resistance to endocrine therapy and are associated with metastatic disease." (PMID 39702552, 2024). "Beyond resistance, the potential role of ESR1 mutations in promoting metastatic disease was recently investigated." (PMID 37046848, 2023). "This ESR1 difference between primary and metastatic tumors suggests that ESR1 mutation emerges during metastasis." (PMID 37371673, 2023). "Our findings identified more acquired activating ESR1 mutations within metastatic diseases, demonstrating that metastatic tumor cells with ESR1 mutations are most frequently acquired under the aromatase inhibitor therapy." (PMID 34146382, 2022). "A series of studies has demonstrated that the incidence of ESR1 mutations is as high as 11–55% in metastatic tumors samples from patients who previously underwent aromatase-inhibitor (AI) treatment." (PMID 35501333, 2022). "To link this finding to hyperactive ESR1 mutations, we reproduced this analysis on metastatic tumors from MET500 and POG570 cohorts." (PMID 35538119, 2022). "ESR1 mutations reside in the ligand binding region and occur in up to 30% of mBCs, but are only detected at low frequencies in primary non-metastatic tumors." (PMID 36140723, 2022). "ESR1 mutations occur almost exclusively in metastatic disease that recurs after endocrine therapy, the most common ESR1 mutations cause ER to retain an active conformation without estrogen binding." (PMID 34717714, 2021). "In this study, we aimed to describe the prevalence of ESR1 mutations in early recurrence events, local recurrence, and newly diagnosed metastasis compared to heavily treated metastatic disease." (PMID 32014063, 2020). "We confirmed the significant enrichment for ESR1 mutations in metastatic tumors (18.3% in metastases vs. 2.2% in local disease, p<3e-80)." (PMID 32374727, 2020). "The development of targeted therapy against ESR1 mutations is an active area of research with great promise for treating metastatic disease, and a deeper understanding of how specific mutations function in vivo will be crucial for optimizing patient outcomes." (PMID 32374727, 2020). "Emerging evidence now suggests that chromosomal rearrangement events involving ESR1 are yet another ESR1 mutational mechanism driving endocrine therapy resistance and metastatic disease progression." (PMID 31106278, 2019). "In the same study, the authors explored the correlation between the frequency of ESR1 mutations detected in ctDNA in patients with metastatic disease (N = 68), and the number of treatment lines received in the metastatic setting." (PMID 31795152, 2019).
metastatic disease (continued). "Recently, with the advancement of sequencing techniques, recurrent mutations on ESR1 have been found to occur more frequently than expected in patients with ERα+ metastatic disease and contribute to acquired endocrine therapy resistance." (PMID 29462880, 2018). "Previous studies have shown that the ESR1 endocrine resistance mutations are rarely detected in primary treatment naive tumors and evolve predominantly in metastatic disease under the selective pressure of endocrine treatment." (PMID 30083595, 2018). "We next studied the association of fulvestrant treatment for metastatic disease and ESR1 and PIK3CA mutations." (PMID 30083595, 2018). "We did not detect a significant association between the tamoxifen treatment for metastatic disease and the prevalence of the ESR1 mutations." (PMID 30083595, 2018). "The clinical status of the metastatic disease at the time of the plasma collection was strongly linked to the detection of ESR1 and PIK3CA mutations in cfDNA." (PMID 30083595, 2018). "Characteristics associated with ESR1 mutation were sensitivity to prior ET, bone metastases, and prior lines of therapy for metastatic disease." (PMID 28361033, 2017). "They noted that ESR1 mutations were present in only 6/183 (3%) primary tumors but in 5/44 (11%) metastatic tumors." (PMID 25928204, 2014). "The BOLERO-2-based dataset indicated enrichment in ESR1 gene mutations from primary tumor samples (7%) compared with metastatic tumor samples (19%)." (PMID 25032257, 2014). "ESR1 mutations have been previously observed to be a common cause of acquired resistance to ET and are well documented as a genomic feature of progressive or metastatic disease on adjuvant antihormone therapies." (PMID 41123599, 2025). "However, there is a lack of comprehensive studies comparing matched primary and metastatic samples for eliminating the possibility that ESR1 mutations identified in metastatic disease were already present in a rare subclone of the primary tumor." (PMID 39594781, 2024). "After exposure to nonsteroidal AIs for metastatic disease, 29–39% of patients harbor ESR1 mutations, whereas ESR1 mutations are quite rare in primary tumors (only ~3% of patients) and newly diagnosed metastatic disease after adjuvant treatment with AIs (5.3–6.4% of patients)." (PMID 37686693, 2023). "In addition, prolonged AI treatment can result in point mutations in the ligand binding domain of ESR1 (mutant ESR1, mESR1), particularly in metastatic tumors, which result in constitutive activation." (PMID 34359625, 2021). "ESR1 mutations in plasma ctDNA appear in patients who have received endocrine therapy, are highest in patients with metastatic disease, and may help guide future therapy." (PMID 34771462, 2021). "To examine the sensitivity and specificity of ESR1 mutant detection in cfDNA compared to detection in tissue biopsies both tested by ddPCR, we tested for the ESR1 mutations in a subset of 23 patients from whom contemporaneous metastatic tumor biopsies were available." (PMID 30083595, 2018). "In addition, patients who had relapsed metastatic disease were more likely to have detectable cfDNA ESR1 mutations (p-value = 0.016 for ESR1), compared to patients who presented with de novo metastatic breast cancer." (PMID 30083595, 2018). "However, the prevalence of ESR1 mutations in metastatic tumors that have recurred or progressed after endocrine therapy is far higher." (PMID 29192207, 2017). "However, after patients experienced their first relapse, 5.3% (2/38) of them had mutated ESR1 in ctDNA, and when the metastatic tumor was treated for the first time, 33% (7/21) of the patients receiving AI had mutated ESR1 in ctDNA, compared to zero patients who received chemotherapy." (PMID 40282403, 2025). "Interestingly, ESR1 mutations were found in ER+ metastatic tumors from patients who were resistant to endocrine therapy, suggesting that ESR1 mutations may be driver events in mBC progression." (PMID 36140723, 2022).
metastatic disease (continued). "Contrastingly, research focusing on the genomic characterization of metastatic BC has shown that ESR1 mutations are more frequent in advanced endocrine receptor positive disease, occurring at a frequency of 12% (9/76; 95% confidence interval (CI), 6–21%) in metastatic tumors." (PMID 31795152, 2019). "ESR1 mutations are rarely acquired during adjuvant AI but are commonly detected after therapy for metastatic disease, suggesting that mechanisms of resistance to targeted therapy may be substantially different between the treatment of micrometastatic and overt metastatic cancer." (PMID 28361033, 2017). "Understanding these ESR1 changes offers potential avenues for developing treatments to improve outcomes in patients with advanced, metastatic disease." (PMID 41155227, 2025). "Strong associations emerged between mutations in ESR1, GATA3, and PIK3CA in metastatic tumors, particularly ESR1 mutations at positions 380, 536, 537, and 538 pairing with PIK3CA mutations at positions 542, 545, and 1047." (PMID 40758706, 2025). "It should be noted that ESR1 alterations were also found in a few tumors sampled from patients with de novo metastatic disease prior to 1L." (PMID 38388477, 2024). "Similar to BCK-high ER+ tumors, ESR1 mutant metastatic tumors exhibited higher immune scores compared to those with ESR1 WT." (PMID 35440136, 2022). "We next sought to extend our findings to clinical specimens using RNA-seq data composed of 51 intra-patient matched ER+ primary-metastatic tumor pairs (7 ESR1 mutant and 44 ESR1 WT pairs)." (PMID 35440136, 2022). "Endocrine resistance turns out to be related to genomic and epigenetic mechanisms, such as the activating mutation of ESR1 (the most frequent one, detectable in 40% of patients with metastatic disease) and the hypermethylation of estrogen receptor promoters." (PMID 35330128, 2022). "Although these ESR1 gene fusions are relatively rare, they are enriched in ET resistant metastatic disease." (PMID 36686845, 2022). "The aim of this study is to evaluate the concordance between ESR1 status in metastatic tumor specimens and matched circulating tumor DNA (ctDNA)." (PMID 33777770, 2021). "Interestingly, the fact that high estrogen response early score was associated with better prognosis in metastatic tumors and the hazard ratio of the score was higher than that of ESR1 expression indicated that the score may be useful as a predictive biomarker for metastatic breast cancer." (PMID 33260779, 2020). "Overall, the plasma and metastatic tumor samples were highly concordant with 100% sensitivity and 88% specificity for the plasma ESR1 cfDNA assay compared to testing metastatic tissue samples applying ddPCR." (PMID 30083595, 2018). "To investigate whether GR signaling impinges on ER+ breast cancer metastatic disease progression and animal survival, we used the clinically relevant metastatic and endocrine therapy-resistant ESR1 mutant MCF-7 D538G and Y537S cells." (PMID 41261233, 2026). "Of note, the rate of ESR1 mutation was not significantly different between the patients who developed metastatic disease and those who did not." (PMID 40647516, 2025). "ESR1 mutation detection rate was not different between patients with de novo metastatic disease (11/53) and patients who relapsed after adjuvant treatment (11/50)." (PMID 32466779, 2020).
metastatic disease (continued). "To conclude, no patient had an identical ESR1 mutation in the early and metastatic disease in the retrospective ILC series." (PMID 30820448, 2019). "With regard to the type of mutations present in ILC, we observed that D538G is the most common mutation, present in the metastatic disease from 57.1%, 56.3%, and 60.0% of the ILC patients with ESR1-mutated metastases from our series, MSKCC-IMPACT, and the SoFEA/PALOMA-3 ctDNA, respectively." (PMID 30820448, 2019). "To conclude, we have shown here using the largest series of matched primary/metastasis ILC cohort and an ultra-sensitive technology, that there was no patient presenting an identical ESR1 mutation in the early setting and in metastatic disease." (PMID 30820448, 2019). "However, studies employing next generation sequencing (NGS) showed that ESR1 amplification in either primary or metastatic tumor is quite rare, occurring at a rate below 2%, thus reflecting a minor role in endocrine resistance." (PMID 31795152, 2019). "Recently, other ESR1 gene fusions have been identified in ER-positive metastatic disease and whether they also utilize the proteasome for their activity should be further investigated." (PMID 29748621, 2018). "Interestingly, patients who received palbociclib for metastatic disease were less likely to have detectable ESR1 mutations in cfDNA but this was not the case for PIK3CA mutations (p-value = 0.01)." (PMID 30083595, 2018). "In addition, chemotherapy treatment, either adjuvant or for metastatic diseases, did not influence the prevalence of the ESR1 mutations." (PMID 30083595, 2018). "In this study, we show that elacestrant is associated with a median TTNT exceeding 6 months in a heavily pretreated real-world population with ESR1-mutant MBC and a numerically longer TTNT of 8.8 months when used early in the metastatic disease course." (PMID 41201834, 2026). "When revisiting the metastatic tumors stratified by APUC-6 levels, we found that tumors with high APUC-6 expression had increased expression of ESR1, ESR2, and PGR, but reduced expression of AR." (PMID 39207857, 2024). "Moreover, the presence of ESR1 mutation in ctDNA of three patients lacking ESR1 mutations in the tissue suggests that liquid biopsy may capture the heterogeneous genetic landscape of metastatic tumors." (PMID 33777770, 2021). "Here, while ESR1 expression is not routinely maintained, the metastatic tumors (including lung, liver, lymph nodes, and adrenal) consistently sustain or harbor increases in AIB1 mRNA expression in comparison with the primary tumors (P = 0.0329)." (PMID 33420368, 2021). "(40%) eventually progressed to metastatic disease compared to WT ESR1 patients (30%), but this and other outcomes were not significantly different." (PMID 32014063, 2020). "Although none of the fusion partners from endocrine-refractory, metastatic disease observed in our studies are known ER targets, additional studies are needed to better understand the diversity of preferred ESR1 partner genes." (PMID 31106278, 2019). "Of these, the two ESR1 fusions identified from endocrine therapy-refractory, ER+ metastatic disease, ESR1-e6>YAP1 and ESR1-e6>PCDH11X, drove endocrine therapy resistant proliferation in experimental models, while ESR1-e6>NOP2 from an endocrine therapy naïve primary tumor did not." (PMID 30525098, 2018).